NLRP3 (NLR family pyrin domain containing 3)
Diseases named in the same sentence as NLRP3 in open-access papers (continued):
Sharing a sentence is not in itself a finding about the gene and the disease.
liver fibrosis (continued). "In this study, we focus our investigation on the role and mechanism of CDCA in the activation of NLRP3 inflammasome, and the effect of inflammasome inhibition on the liver fibrosis in the bile duct ligation (BDL) mouse model." (PMID 27924062, 2016). "To determine if deletion of Nlrp3 or Nlrc4 influences known components in development of liver fibrosis, we measured α-SMA mRNA and hydroxyproline expression." (PMID 24453428, 2013). "Moreover, it decreases inflammation at least in part by downregulating the activity of the NLRP3 inflammasome, and consequently lessens the development of liver fibrosis." (PMID 41493825, 2026). "p-hydroxycinnamic acid, a natural phenolic compound, was reported to suppress the TLR4/NF-κB signaling pathway, reduce IL-1β precursor expression, and attenuate NLRP3 inflammasome activation in a mouse model of high-fat, high-sucrose diet-induced liver fibrosis, thereby inhibiting HSCs activation." (PMID 40661312, 2025). "Its strong anti-inflammatory effects and ability to modulate fibrotic progression suggest that NLRP3 inflammasome inhibition may be a promising therapeutic strategy not only for prevention but also for reversal of liver fibrosis." (PMID 40521185, 2025). "However, the role of NLRP3 in the metabolism of bile acids and gut microbiota in liver fibrosis is unclear, which contributes to the understanding of the mechanism of NLRP3 in liver fibrosis." (PMID 40689656, 2025). "Milk-derived exosomes encapsulated with forsythiaside A specifically targeting CD44 could attenuate liver fibrosis by NLRP3-mediated pyroptosis." (PMID 40667485, 2025). "Our previous study also demonstrated that knockout of NLRP3 can alleviate liver fibrosis." (PMID 40689656, 2025). "Taken together, NLRP3 damages the liver, reduces BA production, and could induce bacterial translocation into the liver to promote liver fibrosis." (PMID 40689656, 2025). "Additionally, the study demonstrated that the NLRP3 inflammasome plays a key role in the progression of liver fibrosis." (PMID 40225863, 2025). "The current study contributes to the understanding of the mechanism of NLRP3 in liver fibrosis and may provide intervention methods for liver fibrosis caused by damage-associated molecular patterns." (PMID 40689656, 2025). "Taken together, NLRP3 damaged the liver and reduced BAs production and might induce bacterial translocation into the liver to promote liver fibrosis." (PMID 40689656, 2025). "Activation of the NLRP3 inflammasome occurs in liver fibrosis." (PMID 40689656, 2025). "Additionally, research has demonstrated that mice overexpressing NLRP3 can spontaneously develop liver fibrosis." (PMID 40406118, 2025). "Notably, the NLR family pyrin domain containing 3 (NLRP3) inflammasome plays a significant role in the mechanisms underlying MASLD and liver fibrosis." (PMID 40427707, 2025). "A recent study found that, in a mouse model of CCl4-induced liver fibrosis, the Citrus aurantium extract astragalin inhibited the expression of TNF-α, IL-18, and IL-1β mRNAs in the livers of fibrotic mice through the NF-κB/NLRP3 inflammasome pathway, significantly ameliorating liver fibrosis." (PMID 39995661, 2025). "NLRP3 inflammasome activation in bone marrow-derived macrophages leads to liver fibrosis." (PMID 40305201, 2025). "In a mouse model of cholestatic liver injury, MCC950 application significantly reduces the production of proinflammatory cytokines and incidence of hepatocyte death and attenuated cholestatic liver injury and liver fibrosis by inhibiting NLRP3 activation and assembly." (PMID 40667485, 2025). "NLRP3 expression is of importance in preclinical models of MASLD, as a loss of function improves liver inflammation and a gain of function worsens liver disease and associated liver fibrosis." (PMID 38672492, 2024). "Activation of FXR or NLRP3 knockout or knockdown can reduce liver fibrosis." (PMID 38172440, 2024).
liver fibrosis (continued). "Patients with post-MAFLD hepatic fibrosis had significantly higher relative gene expression levels of IL-1β and NLRP3; with IL-1β > 1.1 had AUC of 0.919, sensitivity of 88.33, specificity of 96.26, PPV of 96.4, and NPV of 88 and 92.3 accuracy (p value < 0.001)." (PMID 39179677, 2024). "Furthermore, the role of IL-18 in activating HSCs and fostering liver fibrosis has been demonstrated, as the antagonism of IL-18 reduces collagen deposition and enhances metalloproteinase activity in myeloid-specific NLRP3 gain-of-function mutant mice." (PMID 39770566, 2024). "The present study provides novel evidence for the possible involvement of IL-1β and NLRP3 inflammasome in metabolic-associated fatty liver disease pathogenesis and could be valid markers for the early detection of post-MAFLD hepatic fibrosis." (PMID 39179677, 2024). "A significant increase in the mean relative gene expression levels of both IL-1β and NLRP3 found in patients with early fibrosis (F0-F1-2); 31.97 ± 11.8 and 6.76 ± 2.18, respectively; compared with patients with advanced hepatic fibrosis stages (F2-F3); 2.62 ± 3.71 and 4.27 ± 2.99 (p < 0.001 each)." (PMID 39179677, 2024). "The activation of hepatic stellate cells and liver fibrosis may be driven by the activation of the NLRP3 inflammasome." (PMID 39275255, 2024). "Evidence suggests that autophagy and NLRP3 inflammasomes play an important role in liver fibrosis." (PMID 38182564, 2024). "HFPO-TA promotes liver fibrosis through mtROS/cGAS-STING/NLRP3-induced pyroptosis." (PMID 39183465, 2024). "By performing HE, Masson’s trichrome, and Sirius Red staining, we found a significant liver fibrosis and collagen formation in CCl4 mice than in oil mice, while NLRP3−/− mice after CCl4 intervention had significantly weaker fibrosis than the mice in the CCl4 group." (PMID 38172440, 2024). "Furthermore, we showed that the NF-κB/NLRP3 inflammasome pathway was activated in LPS-induced LX-2 cells and CCl4-treated mice with liver fibrosis." (PMID 36983568, 2023). "To clarify the role of NLRP3 in liver fibrosis, we further tested whether Asp had an effect on gene NLRP3 expression in liver fibrosis." (PMID 36983568, 2023). "The concept that SIRT1 serves as a negative regulator of NLRP3 in hepatocytes is strengthened by the fact that deletion of SIRT1 in hepatocytes leads to NLRP3+ cell elevation and severe liver fibrosis in young mice, mimicking the effect of aging on NLRP3 signaling." (PMID 36999514, 2023). "Here we examine whether NLRP3 inhibition modulates age‐ and alcohol‐induced liver fibrosis by evaluating the efficacy of MCC950, a small‐molecule NLRP3 inhibitor." (PMID 36999514, 2023). "The treatment method works by inhibiting the NLRP3-mediated anti-inflammatory activity and Nrf2-mediated antioxidant activity, leading to a reduction in liver angiogenesis and an overall improvement in hepatic fibrosis." (PMID 38155904, 2023). "NLRP3 inhibition by MCC950 ameliorates alcohol‐induced liver fibrosis in old mice." (PMID 36999514, 2023). "To investigate whether Asp regulates liver fibrosis by regulating the NLRP3 signal, we first validated the role of NLRP3 and ARRB2 on liver fibrosis to further evaluate the role of the inflammasome in hepatic fibroblast activation." (PMID 36983568, 2023). "Conversely, hepatocytes with Nlrp3-deficiency and/or pharmacological inhibition of Nlrp3 ameliorate liver inflammation by reducing IL-1β, IL-6, and TNF-α production; they also ameliorate liver fibrosis by reducing Col1a and aSma." (PMID 37564649, 2023). "Similarly, in the CCL4-induced liver fibrosis model, alpinetin and auranofin also exert antiinflammatory and antioxidant effects by blocking the NLRP3 inflammasome." (PMID 37370025, 2023). "Therefore, the NLRP3 inflammasome pathway is a promising therapeutic target for preventing and treating liver fibrosis." (PMID 36983568, 2023).
liver fibrosis (continued). "Given that IL‐1β promotes HSC differentiation into myofibroblasts, it is conceivable that inhibition of IL‐1β by MCC950 may explain the therapeutic effect of NLRP3 inhibition on age‐related liver fibrosis." (PMID 36999514, 2023). "P2X7R-mediated NLRP3 activation involved in IL-1β production by hepatic stellate cells may be associated with extracellular matrix deposition, suggesting that blocking the P2X7R-NLRP3 axis may be a potential therapeutic target for liver fibrosis." (PMID 37081882, 2023). "We hypothesized that NS3TP1 interfered with liver fibrosis by targeting the NF-κB/NLRP3 inflammasome pathway." (PMID 36983568, 2023). "If so, how Asp regulated NLRP3 inflammasome in liver fibrosis and whether any other mechanisms existed by which Asp regulated liver fibrosis needed investigation." (PMID 36983568, 2023). "Meng’s results suggested that NLRP3 inflammasome activation in HSCs might serve as an early mechanism to turn on the inflammatory response and thereby induce liver fibrosis during Schistosoma infection." (PMID 36983568, 2023). "Several studies indicate that NLRP3 inflammasomes could induce tissue damage and liver fibrosis in NASH." (PMID 37805545, 2023). "Moreover, research has shown that mice overexpressing NLRP3 spontaneously developed to hepatic fibrosis." (PMID 38086792, 2023). "Furthermore, cholangiocytes, which play a pivotal role in liver fibrosis, have been demonstrated to generate pro-inflammatory cytokines and compromise the epithelial barrier function upon activation by NLRP3." (PMID 37685870, 2023). "Besides, new results identify hepatocyte pyroptosis and release of NOD-like receptor family pyrin domain containing 3 (NLRP3) inflammasome components as an additional mechanism to propagate liver injury and liver fibrosis development in MASH progression." (PMID 39086681, 2023). "The NLRP3 inflammasome plays an important role in the development of liver fibrosis." (PMID 36834849, 2023). "Importantly, the activation of the NLRP3 inflammasome is closely related to the progression of hepatic fibrosis." (PMID 36834849, 2023). "Besides its inhibition of HBV replication, EGCG was found to repress macrophage NLRP3 inflammasome activation, a critical aggravator of liver fibrosis progression in mice." (PMID 37122751, 2023). "Therefore, the activation of NLRP3 inflammasome can activate HSCs, thus resulting in the occurrence and development of liver fibrosis." (PMID 35371052, 2022). "Furthermore, inhibiting NLRP3 inflammasome-dependent pyroptosis effectively attenuated liver injury and fibrosis severity in a carbon tetrachloride (CCl4)-induced liver fibrosis mouse model." (PMID 36429008, 2022). "Given this, we hypothesized that S100A8 and/or S100A9 may regulate NLRP3 inflammasome-dependent pyroptosis to establish a proinflammatory microenvironment, thereby potentiating the progression of liver fibrosis." (PMID 36429008, 2022). "NLRP3 depletion in primary mouse HSCs attenuated liver fibrosis in the presence of aldosterone, indicating the crucial role of NLRP3 inflammasome in aldosterone-mediated liver fibrosis." (PMID 35707547, 2022). "In vivo experiments have shown that it could reduce liver fat content, alleviate the expression of liver fibrosis indicators and autophagy, and inhibit the expression of NLRP3, ASC, caspase-1, and IL-1β." (PMID 36016562, 2022). "Here, we investigated whether NLRP3 inflammasome-dependent pyroptosis could be an intervention target for liver fibrosis." (PMID 36429008, 2022). "NOX4 and NLRP3 are emerging as liver fibrosis therapy targets." (PMID 36290765, 2022). "Therefore, we used ER knockout mice to carry out experiments, and obtained strong evidence to support that SSd has ERβ pathway-dependent anti-liver fibrosis effects, such as inhibiting the expression of NLRP3 inflammasome proteins." (PMID 35694250, 2022).
liver fibrosis (continued). "By establishing liver fibrosis models using wild-type and ERKO mice, we demonstrated that SSd could alleviate liver fibrosis by inhibiting the ROS/NLRP3 inflammasome axis through activating the ERβ pathway." (PMID 35694250, 2022). "Here, we further explored whether S100A8 can promote liver fibrosis by inducing NLRP3 inflammasome-dependent pyroptotic death in macrophages." (PMID 36429008, 2022). "So, hepatocyte pyroptotic cell death may be a novel mechanism of NLRP3‐mediated liver injury and blocking the NLRP3 pathway could be a promising target to attenuate liver fibrosis." (PMID 35415891, 2022). "It is known that TGF-β is a master profibrogenic cytokine and a promising target to treat fibrosis, but a clear mechanism by which TGF-β causes liver fibrosis via the NLRP3 inflammasome is not yet understood." (PMID 35138513, 2022). "Based on the role of S100A8-elicited NLRP3 pyroptosis in liver fibrosis, we chose a well-defined cohort of liver fibrosis patients to assess the clinical importance of circulating S100A8, GSDMD, IL-1β, and IL-18 for predicting the occurrence and progression of disease." (PMID 36429008, 2022). "In addition to NLRP3, other inflammasomes in hepatocytes are also involved in liver injury and liver fibrosis." (PMID 35707547, 2022). "PA can reduce PBC-induced liver fibrosis in mice and may function by curbing the formation of NLRP3." (PMID 35195182, 2022). "Here, we observed that the macrophage was the major cell type that underwent NLRP3 inflammasome-dependent pyroptosis in liver fibrosis, which could be mediated by S100A8-induced Toll-like receptor 4 (TLR4)/NF-κB activation and ROS generation." (PMID 36429008, 2022). "Recently, a study showed that ursolic acid, a natural terpenoid isolated from a variety of herbal medicine, decreased collagen deposition and fibrosis-related factors expression and inhibited the level of NADPH oxidase 4 (NOX4) and NLRP3 in the CCl4-induced liver fibrosis model." (PMID 36160411, 2022). "Taken together, TGF-β may play an important role in hepatic fibrosis progression through the TGF-β autocrine loop by NLRP3 inflammasome activation in LX-2 cells." (PMID 35138513, 2022). "Moreover, they can inhibit the expression of NLRP3, HSCs activation, and liver fibrosis by acting on different estrogen ligands." (PMID 35694250, 2022). "Moreover, both NLRP3 inflammasome components, deficient or treated with NLRP3 inhibitors, attenuated the inflammation, liver fibrosis, and liver cell death in a mouse model, which further demonstrated the role of the NLRP3 inflammasome in NAFLD." (PMID 36160411, 2022). "It seems that the NLRP3 inflammasome in hepatocytes may play a pivotal role in developing liver fibrosis." (PMID 35707547, 2022). "Moreover, after activation of NLRP3 inflammasome, hepatocytes can undergo pyroptosis, with subsequent release of NLRP3 inflammasome particles that stimulate stellate cell activation and amplify liver fibrosis." (PMID 35350750, 2022). "In animal models of NAFLD, inhibition of NLRP3 may considerably improve the prognosis and liver fibrosis." (PMID 36110858, 2022). "Also, in a bile duct ligation (BDL) model for cholestasis, MCC950 has been demonstrated to reduce liver fibrosis through inhibiting NLRP3 and the mechanism was partially attributed to inhibition of Toll-like receptor signaling." (PMID 34869447, 2021). "Furthermore, MyD88 in macrophages enhanced CXCL2 secretion and activated NLRP3 inflammasome in HSCs, which in turn promoted liver fibrosis." (PMID 34830293, 2021). "Based on the notion that the NLRP3 inflammasome plays a key role in liver fibrogenesis, the potential for clinical use of auranofin to treat liver fibrosis was assessed in two experimental liver fibrosis models." (PMID 34193972, 2021).
liver fibrosis (continued). "NOD-like receptor protein 3 (NLRP3) inflammasome inhibitor, MCC950, is first demonstrated to ameliorate nonalcoholic fatty liver disease (NAFLD) and fibrosis in obese diabetic mice, and the targeting of NLRP3 is a logical direction in pharmacotherapy for liver fibrosis." (PMID 34594474, 2021). "It is clear that NLRP3 is involved in the pathogenesis of liver fibrosis with NAFLD." (PMID 33937277, 2021). "Pelargonidin could prevent liver fibrosis via Nrf2-inhibited ROS/NLRP3/IL-1β axis and inhibit inflammasome-related genes and IL-1β secretion in a dose-dependent manner." (PMID 33552591, 2021). "NLRP3 can directly activate HSCs, triggering liver fibrosis." (PMID 35187072, 2021). "It has been reported that NLRP3 inflammasome plays an important role in liver fibrosis development." (PMID 34830293, 2021). "In addition, NLRP3 also induced HSC activation and collagen deposition, thereby causing liver fibrosis." (PMID 33937277, 2021). "We wonder whether the NLRP3 inflammasome activated in HSCs directly contributed to liver fibrosis development." (PMID 34830293, 2021). "Given that MCD feeding induced hepatic fibrosis in ApoE-/- mice, we tested whether the inhibition of NLRP3 with IFM-514 had an effect on markers of fibrosis." (PMID 34513923, 2021). ", proved to ameliorate P2X7 receptor-mediated NLRP3 (nucleotide-binding oligomerization domain, leucine-rich repeat, and pyrin domain-containing 3) inflammasome and hepatic fibrosis through inducing LXRα/β pathway in the development of thioacetamide-stimulated hepatic fibrosis mice." (PMID 35069197, 2021). "Furthermore, it has been reported that in the mouse NASH model, mtDNA released by KCs bound and activated the NLRP3 inflammasome to induce interleukin (IL)-1β and IL-18, triggering proinflammatory responses and resulting in liver fibrosis." (PMID 35187072, 2021). "In NLRP3−/- mice, we showed for the first time that UA could reverse liver fibrosis by inhibiting the expression of the NLRP3 inflammasome." (PMID 34530693, 2021). "In this study, we found that UA could alleviate CCI4 induced liver fibrosis, and proposed that the beneficial effect of UA on liver fibrosis may be achieved through the NOX4/NLRP3 inflammasome signaling pathway and improving intestinal bacteria." (PMID 34530693, 2021). "In this study, we employ calcipotriol, a potent VDR agonist, to test its therapeutic effect in cholestasis, determine whether VDR can modulate NLRP3 to inhibit HSC activation and alleviate liver fibrosis and injury, and explore the underlying mechanism." (PMID 32296329, 2020). "Previous studies demonstrated that NF-κB/NLRP3 signaling pathway promoted liver fibrosis in mice." (PMID 33188176, 2020). "Notably, we found that VDR activation can induce YAP1 expression at the transcriptional level in liver tissue and HSC line and increased YAP1 further exerts its inhibitory effect on NLRP3 expression to alleviate cholestatic liver fibrosis and injury." (PMID 32296329, 2020). "However, excessive NLRP3 inflammasome activation, which contributes to inflammatory liver injury and development of liver fibrosis should be tightly controlled." (PMID 32296329, 2020). "However, ASK1 inhibition with selonsertib significantly reduces liver fibrosis in Nlrp3 KI mice (as demonstrated by a 33.5% reduction in hydroxyproline levels when compared to untreated Nlrp3 KI controls)." (PMID 32060587, 2020). "The present study is the first to demonstrate that deAND ameliorates steatohepatitis, liver fibrosis, and liver damage partially by enhancing hepatic Nrf2-mediated downstream antioxidant enzyme activities and suppressing NLRP3 inflammasome activation in HFHC diet-induced fatty liver disease." (PMID 32085637, 2020). "Therefore, NLRP3 inflammasomes play a potential role in the activation of HSCs and the development of liver fibrosis, but there are few relevant studies so far." (PMID 32733951, 2020).